PBX1 (PBX homeobox 1)
Diseases named in the same sentence as PBX1 in open-access papers (continued):
Sharing a sentence is not in itself a finding about the gene and the disease.
breast carcinoma (continued). "Genes MIR124-2, PBX1, SKI, GHSR and RBPMS were reported to be associated with breast cancer, and a gene CYP19A1 was reported to be be associated with endometrial cancer." (PMID 31640538, 2019). "Using the cell line MCF7 as model to investigate the activation of oncogenic ERα target genes during breast cancer progression, the study identified PBX1 as “partner” pioneer factor to FOXA1." (PMID 28261581, 2017). "Although previous studies have reported that PBX1 can promote melanoma, breast cancer and lung cancer, the role that this protein plays in GC is unclear." (PMID 28514754, 2017). "PBX1 has been shown to be a downstream target of NOTCH signaling in breast cancer, and NOTCH itself is a known regulator of CSCs." (PMID 27285982, 2016). "While several other pioneer factors play a central role in modulating ERα binding in breast cancer cells, our data suggest that PBX1 has some unique properties." (PMID 26215677, 2015). "In agreement, PBX1 protein levels are significantly upregulated during metastatic progression in ERα-positive breast cancer patients." (PMID 26215677, 2015). "More importantly, PBX1 was one of the only two transcripts (the other being PVRL4) carrying evidence of prognostic significance in the ERα-positive breast cancer subtype (METABRIC)." (PMID 26215677, 2015). "PBX1 amplification was confirmed in the circulating free DNA (cfDNA) of metastatic patients further suggesting the potential for using PBX1 to monitor breast cancer progression." (PMID 26215677, 2015). "Correspondingly, ERα-positive breast cancer patients carrying PBX1 amplification are characterized by poor survival." (PMID 26215677, 2015). "We also established the significance of PBX1 mRNA and protein level as a prognostic biomarker in several independent large cohorts of primary breast cancers." (PMID 26215677, 2015). "When we looked at genes potentially co-amplified with PBX1 (chr1q23.3) we found that very few candidates were also over-expressed in breast cancer." (PMID 26215677, 2015). "Our results demonstrate that PBX1 is required to direct EGF-ERα signalling at the chromatin level in breast cancer cells." (PMID 26215677, 2015). "We collected 20 biopsies from primary ERα-positive breast cancers and compared PBX1 protein levels with matched relapses (all endocrine treated, average time to relapse = 44.4 ± 35 months)." (PMID 26215677, 2015). "Our results show that ERα-positive breast cancer patients with elevated PBX1 staining intensity at diagnosis (over 90% positive staining) develop metastatic disease significantly faster than patients with lower staining intensity." (PMID 26215677, 2015). "We then restricted our analysis to ERα-positive breast cancer patients from the published TCGA data to exploit the more complete clinical annotations and found that 28/364 (8%) carried potential PBX1 amplification/overexpression." (PMID 26215677, 2015). "We have thus investigated the role of PBX1 in mediating EGF signalling in ERα-positive breast cancer cell lines using genome wide-analyses including microarray and ChIP-seq." (PMID 26215677, 2015). "This group of genes included three transcriptional activators PBX1, SOX4 and ETS2, which have been linked to breast cancer tumorigenesis." (PMID 23301048, 2013). "The PBX1-HOX heterodimer complex was found to contribute to oncogenic activity in breast cancer and melanoma." (PMID 22567123, 2012). "In agreement, we demonstrate that PBX1 depletion in MCF7 breast cancer cells seen at the mRNA and protein level also significantly decreases its occupancy on the chromatin." (PMID 22125492, 2011). "Analyses of 41 independent breast cancer expression profile studies, such as van de Vijver study, demonstrate that PBX1 and ERα are also co-expressed in primary breast tumors (p = 2.72e-13 for the van De Vijver study and p≤1e-4 for all other studies)." (PMID 22125492, 2011).
breast carcinoma (continued). "Correspondingly, PBX1 expression alone can discriminate a priori the outcome in ERα-positive breast cancer patients." (PMID 22125492, 2011). "Overall these results support a functional role for PBX1 in mediating the response to estrogen in ERα-positive breast cancer." (PMID 22125492, 2011). "Here we demonstrate that PBX1 acts as a pioneer factor guiding ERα genomic activity in breast cancer." (PMID 22125492, 2011). "Overall, this study defines the mechanisms dependent on the pioneer factor PBX1 that drives an aggressive response in a subset of ERα-positive breast cancers." (PMID 22125492, 2011). "In agreement with a role for PBX1 in breast cancer, PBX1 depletion completely prevented the estrogen-induced proliferation of MCF7 breast cancer cells." (PMID 22125492, 2011). "In the present study, we have investigated the pioneer function of PBX1 towards ERα genomic activity in breast cancer." (PMID 22125492, 2011). "To assess the prognostic value of PBX1 in breast cancer we performed a meta-analysis using breast tumor expression studies with follow-up data available through Oncomine (Compendia Bioscience, Ann Arbor, MI)." (PMID 22125492, 2011). "To determine if they collaborate with each other at these genomic regions or if they are part of a common complex we profiled FoxA1 binding following PBX1 depletion in estrogen starved MCF7 breast cancer cells." (PMID 22125492, 2011). "Overall, these results reveal that PBX1 acts as a pioneer factor guiding ERα genomic activity independently of FoxA1 in breast cancer." (PMID 22125492, 2011). "Expression profile analysis in MCF7 breast cancer depleted of PBX1 reveals that a 71% of estrogen-induced target genes are dependent on PBX1." (PMID 22125492, 2011). "ChIP-qPCR assays against ERα in PBX1 depleted MCF7 breast cancer cells demonstrate that ERα recruitment following estrogen treatment is dependent on PBX1." (PMID 22125492, 2011). "Immunofluorescence assays against PBX1 in MCF7 breast cancer cells deprived of estrogen demonstrate its localization to the nucleus." (PMID 22125492, 2011). "Here we demonstrate that PBX1 acts as a pioneer factor and is essential for the ERα-mediated transcriptional response driving aggressive tumors in breast cancer." (PMID 22125492, 2011). "To demonstrate that PBX1 occupies the chromatin in MCF7 breast cancer cells we performed a ChIP-seq assay in cells maintained in full media." (PMID 22125492, 2011). "RT-qPCR against other PBX1 genes demonstrates that PBX1 is the predominant family member expressed in ERα-positive breast cancer cells." (PMID 22125492, 2011). "Taken together, these results reveal the intricate interplay between distinct pioneer factors required for the implementation of specific transcriptional response to estrogen in breast cancer and distinguishes PBX1 as a prognostic marker." (PMID 22125492, 2011). "We differentiated breast cancer patients according to high (top 10%) or low (bottom 10%) PBX1 mRNA levels and then generated Kaplan-Meier curves according to the metastasis-free survival status of breast cancer patients." (PMID 22125492, 2011). "In addition, exosomes released by breast cancer cells contain reduced levels of miR-6881-3p, recently shown to target PBX1 in osteoblasts thus negatively regulating the expression of its downstream effectors." (PMID 38404687, 2024). "Therefore, PBX1 upregulation is involved in driving tumorigenesis and metastasis in breast cancer by acting on malignant cells as well as in the tumor microenvironment." (PMID 38404687, 2024). "A positive correlation of PBX1 and ERα expression levels in breast cancer has been demonstrated." (PMID 38404687, 2024). "An interesting concept, brought forward first in the context of skeletal muscle development and later in connection with breast cancer progression, is that PBX1 may be capable of transcriptional pioneering." (PMID 34697387, 2021).
breast carcinoma (continued). "Indeed, a previous study showed that increased expression of PBX1 promotes proliferation of melanoma and breast cancer cells." (PMID 28514754, 2017). "Thus, PBX1 expression seems to be a major determinant for the development and progression of luminal breast cancer patients." (PMID 26215677, 2015). "Our mechanistic study revealed that PBX1 controls the expression of a subset of ERα target genes stimulated by EGF in vitro and may be linked to breast cancer progression." (PMID 26215677, 2015). "PBX1 transcripts are significantly overexpressed in breast cancer when compared to normal tissues." (PMID 26215677, 2015). "To test this hypothesis we performed meta-analysis on METABRIC (Illumina arrays) and The Cancer Genome Atlas (TCGA, RNA-seq data) studies stratifying ERα-positive breast cancer patients in high and low PBX1 expressors." (PMID 26215677, 2015). "We have recently described the role of PBX1 as a novel pioneer factor in ERα breast cancer." (PMID 26215677, 2015). "In light of these observations we hypothesized that PBX1 expression levels could contribute to breast cancer progression in ERα-positive breast cancer patients." (PMID 26215677, 2015). "Our work has identified PBX1 as a novel functional biomarker in ERα-positive breast cancer." (PMID 26215677, 2015). "We recently demonstrated that PBX1 is a pioneer factor in ERα-positive breast cancer, occupying the chromatin prior to ERα binding following its activation with estrogen and regulating the expression of estrogen dependent genes associated with aggressive progression." (PMID 26215677, 2015). "Finally, we investigated PBX1 protein levels in the Tenovus Nottingham cohort of FFPE primary breast cancers (n = 1650)." (PMID 26215677, 2015). "Despite the impossibility to elucidate the temporal details of PBX1 amplification/overexpression, our data strongly suggest that PBX1 upregulation may contribute to breast cancer progression and metastatic development." (PMID 26215677, 2015). "PBX1 has also been demonstrated to be a downstream effector of the Notch signaling pathway, which is frequently activated in ovarian, cervical, and certain types of breast carcinomas." (PMID 22567123, 2012). "It is worthy to note that also the pioneer factor FoxA1 recruits ERα to H3K4me2-enriched regulatory elements in breast cancer cells, but only PBX1 expression correlated with metastasis formation and development of resistance to endocrine therapies in patients with ERα positive breast cancer." (PMID 25436603, 2012). "Moreover, PBX1 acts as a pioneer factor in breast cancer, remodeling the chromatin to favor the recruitment of estrogen receptor alpha (ERa)." (PMID 22567123, 2012). "To assess the relation between genome-wide binding and expression profiles we cross-examined the estrogen responsive gene lists (all estrogen responsive genes and PBX1-dependent estrogen responsive genes) defined in MCF7 breast cancer cells against the binding profiles for ERα, PBX1 and FoxA1." (PMID 22125492, 2011). "Finally, we reveal that PBX1 and FoxA1 can co-occupy specific genomic regions in breast cancer cells." (PMID 22125492, 2011). "This is in agreement with a role for PBX1 as a novel pioneer factor in breast cancer." (PMID 22125492, 2011). "Indeed, PBX1 is the only pioneer factor identified to date that discriminates outcome such as metastasis in ERα-positive breast cancer patients." (PMID 22125492, 2011). "Indeed, PBX1 depletion disrupted only the regulation of shared or PBX1-dependent estrogen target genes in MCF7 breast cancer." (PMID 22125492, 2011). "Together our results reveal that PBX1 is a novel pioneer factor defining aggressive ERα-positive breast tumors, as it guides ERα genomic activity to unique genomic regions promoting a transcriptional program favorable to breast cancer progression." (PMID 22125492, 2011).
breast carcinoma (continued). "Indeed, genome-wide FAIRE-seq assays in MCF7 breast cancer cells reveals that PBX1 occupied chromatin is already highly accessible." (PMID 22125492, 2011). "Thus, by promoting EGF signaling, PBX1 could help breast cancer cells survive estrogen receptor blockade." (PMID 39358487, 2024). "Moreover, PBX1 is known to be amplified in metastatic ER+ breast cancers." (PMID 35774123, 2022). "In addition, we start by considering a cell state in which the source nodes IGF1R_T and PBX1 are ON (IGF1R is a common RTK in breast cancer signaling, and the subscript T denotes the intrinsic transcript level of IGF1R; PBX1 is a co-factor required for ER-dependent transcription)." (PMID 29623959, 2017). "Recently PBX1, involved in diverse developmental processes, was characterized as a novel pioneer factor that may open chromatin at specific genomic locations and recruit estrogen receptor alpha (ERα) to estrogen responsive genes in breast cancer cells." (PMID 25436603, 2012). "Hence, it is fascinating to speculate a role for PBX1 in the development of drug resistance in breast cancer." (PMID 22125492, 2011). "However, the contribution of PBX1 to chromatin structure and epigenetic signatures regulating transcription in ERα-positive breast cancer cells is unknown." (PMID 22125492, 2011). "PBX1 has also been shown to regulate ER-dependent transcription upon PI3K inhibition and to sensitize breast cancer cells further to alpelisib." (PMID 35774123, 2022). "Recent data suggest that KMT2D is involved in the recruitment and activation of relevant breast cancer genes including FOXA1, PBX1, and ER." (PMID 30990809, 2019). "Recent tumour sequencing efforts indicate that PBX1 locus is potentially amplified in 13% of primary breast cancers (TCGA provisional) supporting the hypothesis that genomic amplification may partially explain PBX1 overexpression in breast cancer (TCGA provisional)." (PMID 26215677, 2015). "The hexapeptide motif is one of the regulatory sites in HOXB9 that interacts with cofactors such as Pbx1 to induce downstream gene expression and promote EMT and other tumorigenic events when it is aberrantly expressed such as that observed in breast cancers." (PMID 26536658, 2015). "Immunofluorescence, ChIP-seq assays and ChIP-reChIP against PBX1 and FoxA1 suggests that they co-occupy genomic regions in MCF7 breast cancer cells." (PMID 22125492, 2011). "To address the functional relation between PBX1 and ERα we assessed the role of PBX1 on estrogen-induced growth in the ERα-positive MCF7 breast cancer cells." (PMID 22125492, 2011). "PBX1 mRNA and protein levels were significantly depleted (∼70%) in MCF7 breast cancer cells transfected with one of two independent siRNA against PBX1." (PMID 22125492, 2011). "Sequential ChIP assays (ChIP-reChIP) against ERα and PBX1 in both estrogen treated and untreated MCF7 breast cancer cells demonstrates that both factors co-occupy the same sites following ERα recruitment." (PMID 22125492, 2011). "These correlations were not significant in ERα-negative breast cancer patients further supporting the notion that PBX1 is a key regulator of ERα activity." (PMID 26215677, 2015). "Conversely, PBX1 amplification correlates, although not significantly, with a lower chance of metastatic disease in the limphnodes in ERα negative breast cancer patients (45% vs. 57% respectively)." (PMID 26215677, 2015). "This was also revealed by comparing PBX1 mRNA expression across 47 distinct ERα-positive and negative breast cancer cells (p = 8.98e-7)." (PMID 22125492, 2011). "To test if PBX1 directly impacts ERα genomic activity we first assessed PBX1 occupancy through ChIP-qPCR assays at known ERα binding sites in MCF7 breast cancer cells treated or not with estrogen." (PMID 22125492, 2011).
breast carcinoma (continued). "Profiling PBX1 recruitment and chromatin accessibility across the genome of breast cancer cells through ChIP-seq and FAIRE-seq reveals that PBX1 is loaded and promotes chromatin openness at specific genomic locations through its capacity to read specific epigenetic signatures." (PMID 22125492, 2011). "Comparing FAIRE signal in estrogen starved MCF7 breast cancer cells depleted or not of PBX1 through siRNA revealed a significant decrease in chromatin openness in PBX1-depleted compared to control cells at the majority of tested sites." (PMID 22125492, 2011). "Interestingly, genes that failed to be induced by EGF in PBX1 depleted cells are also significantly enriched in several independent genes datasets obtained from patients characterized by aggressive breast cancers." (PMID 26215677, 2015). "Importantly, PBX1 depletion in MCF7 breast cancer cells did not affect ERα or FoxA1 expression both at the mRNA and protein level." (PMID 22125492, 2011). "Indeed, PBX1 expression correlates with ERα in primary breast tumors, and breast cancer cells depleted of PBX1 no longer proliferate following estrogen stimulation." (PMID 22125492, 2011). "The entire mechanism involving FGF2, PBX1/PBX2, and HOXB7/HOXB8 in breast cancer tumorigenesis is not clear." (PMID 37445737, 2023).